TFG (trafficking from ER to golgi regulator)
Diseases named in the same sentence as TFG in open-access papers (continued):
Sharing a sentence is not in itself a finding about the gene and the disease.
Cushing syndrome (1 paper, 2023). Cushing's syndrome (CS) encompasses a group of hormonal disorders caused by prolonged and high exposure levels to glucocorticoids that can be of either endogenous (adrenal cortex production) or exogenous (iatrogenic) origin. "In summary, we herein have reported gene fusions involving BEND2, BCOR and TFG in four successfully tested ACTH-producing and Cushing syndrome-associated NENs of the pancreas, but not in those from non-pancreatic origin." (PMID 36690805, 2023).
endometriosis (1 paper, 2024). The growth of functional endometrial tissue in anatomic sites outside the uterine body. "The rare CNV gain involving ADGRG7 and TFG genes in this family provides a new candidate genetic marker for future investigations involving familial endometriosis." (PMID 38765507, 2024).
Hepatic steatosis (1 paper, 2024). Steatosis is a term used to denote lipid accumulation within hepatocytes. "TFG deletion in adipocytes markedly exacerbated hepatic steatosis in both experimental settings." (PMID 38681675, 2024).
Histiocytosis (1 paper, 2025). An excessive number of histiocytes (tissue macrophages). "We identified a rare case of ALK-positive histiocytosis with fusion of the ALK gene with TFG." (PMID 40700600, 2025). "KIF5B has been shown to be the most common fusion-partner gene in ALK-positive histiocytosis, whereas CLTC, TPM3, EML4, and TFG have only been infrequently recorded." (PMID 40700600, 2025).
liver cancer (1 paper, 2019). An epithelial or non-epithelial malignant neoplasm that arises from the liver. "This discrepancy suggests the possibility of using TFG as a differential marker between CCA and HCC liver cancers." (PMID 31754244, 2019).
medulloblastoma (1 paper, 2022). A malignant, invasive embryonal neoplasm arising from the cerebellum. "Additional selected linear fusions in medulloblastoma that cannot be interpreted via read-through transcription are the TFG--ADGRG7 and the PVT1--CASC8." (PMID 35804907, 2022). "In fact, the 2 medulloblastoma samples expressing the TFG--ADGRG7 circular fusion also express the TFG--ADGRG7 linear fusion." (PMID 35804907, 2022).
melanoma (1 paper, 2024). A malignant, usually aggressive tumor composed of atypical, neoplastic melanocytes. "The Trk-fusion gene (TFG) was amplified in four melanoma patient plasma samples according to our lcWGS results, but digital PCR also indicated a possible deletion." (PMID 38982214, 2024).
myxoid chondrosarcoma (1 paper, 2024). A chondrosarcoma characterized by the presence of myxoid changes. "TFG gene itself also participates in several oncogenic rearrangements resulting in anaplastic lymphoma and myxoid chondrosarcoma, and may also play a role in the NF-kB pathway." (PMID 38765507, 2024).
Obesity (1 paper, 2024). Accumulation of substantial excess body fat. "Surprisingly, we found TFG expression to be significantly up-regulated in adipose tissues from obese mice, which prompted us to investigate the roles of the TFG in adipogenesis and its potential contribution(s) to obesity development." (PMID 38681675, 2024). "First, we examined whether TFG expression levels are altered in the adipose tissues of mice with genetic or diet-induced obesity." (PMID 38681675, 2024).
osteosarcoma (1 paper, 2021). A usually aggressive malignant bone-forming mesenchymal neoplasm, predominantly affecting adolescents and young adults. "Meanwhile, the immunofluorescence (IF) assay showed positive co‐localization between CLTC and TFG in the osteosarcoma cells." (PMID 34185412, 2021). "The results showed that CLTC knockdown significantly decreased the half‐life of TFG in the osteosarcoma cells." (PMID 34185412, 2021). "In this study, we confirmed that TFG was highly expressed in osteosarcoma tissues when compared with matched normal tissues." (PMID 34185412, 2021). "The qRT‐PCR assay validated the overexpression of TFG after transfection with pCMV‐TFG plasmid in the osteosarcoma cells." (PMID 34185412, 2021). "The IHC results (H score) showed that TFG was significantly more highly expressed in the osteosarcoma tissues than in the matched normal tissues." (PMID 34185412, 2021). "CCK‐8, colony formation, and apoptosis assays confirmed that TFG knockdown attenuated cell proliferation and promoted apoptosis in the osteosarcoma cells." (PMID 34185412, 2021). "Immunohistochemistry (IHC) analysis demonstrated that high expression of TFG was also correlated with a poor prognosis in patients with osteosarcoma." (PMID 34185412, 2021). "In conclusion, our study provides mechanistic insights into the oncogenic effect of CLTC, and understanding of the SP1/CLTC/TFG axis serves a novel therapeutic strategy for patients with osteosarcoma." (PMID 34185412, 2021). "Based on the clinical analysis, the expression of TFG was positively related to the AJCC/TNM stage of patients with osteosarcoma." (PMID 34185412, 2021). "WB and qRT‐PCR assay showed that TFG siRNAs significantly decreased TFG expression in the osteosarcoma cell lines." (PMID 34185412, 2021). "In conclusion, these results confirmed that CLTC interacts with TFG in osteosarcoma cells and promotes the protein stabilization of TFG." (PMID 34185412, 2021). "To better understand the role of TFG in CLTC‐mediated osteosarcoma progression, we first investigated the function of TFG." (PMID 34185412, 2021). "Considering that TFG is a downstream protein of CLTC and has an oncogenic effect, we next hypothesized that CLTC functions in a TFG‐dependent manner in osteosarcoma." (PMID 34185412, 2021). "Down‐regulation of TFG also delayed cell proliferation and promoted apoptosis in osteosarcoma." (PMID 34185412, 2021). "In addition, CLTC and TFG can be used as postoperative pathological indicators to predict the prognosis of patients with osteosarcoma." (PMID 34185412, 2021). "Meanwhile, down‐regulation of both CLTC and TFG was found to activate ER stress in osteosarcoma." (PMID 34185412, 2021). "Two specific siRNAs were utilized to inhibit the expression of TFG in the osteosarcoma cells." (PMID 34185412, 2021). "Thus, inhibition of CLTC or its interaction with TFG provides a valuable approach for developing effective pharmacological strategies for the treatment of osteosarcoma." (PMID 34185412, 2021). "In a further study, TFG was overexpressed in osteosarcoma cells by pCMV‐TFG vectors." (PMID 34185412, 2021). "The deregulation of CLTC and TFG is emerging as a unique target for osteosarcoma." (PMID 34185412, 2021). "To investigate the correlation between TFG and CLTC in clinical samples, we used osteosarcoma TMA to demonstrate their relationship." (PMID 34185412, 2021). "Herein, we identified TFG as an interacting protein of CLTC and as an oncogene in osteosarcoma." (PMID 34185412, 2021).
Parkinson disease (1 paper, 2022). A progressive degenerative disorder of the central nervous system characterized by loss of dopamine producing neurons in the substantia nigra and the presence of Lewy bodies in the substantia nigra and locus coeruleus. "Other studies have also reported that the Wnt signaling is involved in the maintenance of neuronal health in the adult brain and neuroprotection against neurodegenerative diseases such as AD and Parkinson's disease, and may, therefore, offer opportunities for novel therapies for TFG‐related CMT2." (PMID 35986567, 2022).
serous ovarian cancer (1 paper, 2010). "That is, one group including: SSBP1, IFI6 DDT, IFI27, C11orf92, NFKBIA, TNXB, NEAT1 and TFG, was up-regulated in most patients with stage III serous ovarian cancer." (PMID 20969748, 2010).
soft tissue sarcoma (1 paper, 2024). A malignant neoplasm arising from muscle tissue, adipose tissue, blood vessels, fibrous tissue, or other supportive tissues excluding the bones. "TFG participates in chromosomal translocations associated with hematologic tumor and soft tissue sarcomas, and is also involved in the NF-kappa B pathway." (PMID 38765507, 2024).
Thrombocytopenia (1 paper, 2025). A reduction in the number of circulating thrombocytes. "We hypothesized that the TFG::RARA variant APL exerts a relatively limited effect on coagulation function and results in less severe thrombocytopenia." (PMID 40386562, 2025).
tumor (20 papers, 2014 to 2025). "Therefore, we speculated that the change in the host tumor-related gene TFG in the transformed cells might be caused by T. annulata and that the TFG gene is likely to play an important role in cell transformation." (PMID 36337204, 2022). "However, other fusions detected simultaneously in normal and tumour samples (JAK3-INSL3, KANSL1-ARL17A/B and TFG-ADGRG7) could be cancer predisposition ones probably involved in tumour-maintaining tasks." (PMID 30914738, 2019). "Targeted inhibition of TFG by specific silencing RNAs led to reduced proliferation of PC3 tumor cells and induction of premature senescence." (PMID 38982214, 2024). "Consistently, we find TFG::GPR128 broadly expressed across tumor and normal tissues and represented similarly at a median of 2% of all tissues examined." (PMID 37323575, 2023). "Activated TFG protein can promote tumor development and regulate cell size, cell apoptosis and cell proliferation." (PMID 36337204, 2022). "The TFG fusion proteins play a role in oncogenesis, with the activity of TFG fusion proteins promoting tumor development." (PMID 36251702, 2022). "The Kaplan–Meier survival assay indicated that the tumor‐free survival and overall survival of patients with positive TFG expression were significantly shorter than those of the patients with negative TFG expression." (PMID 34185412, 2021). "Mechanistic investigations further revealed that CLTC elicited its pro‐tumor effects by directly binding to and stabilizing trafficking from the endoplasmic reticulum to the Golgi regulator (TFG)." (PMID 34185412, 2021). "In the present study, we demonstrated the aberrant expression of TFG in hyperplasia/dysplasia of bile duct epithelia and tumor tissues of CCA patients and Ov-induced CCA hamsters using UEA-I histochemistry." (PMID 31754244, 2019). "The aberrant expression of TFG during tumor development was shown in Ov-induced CCA hamster models and high expression of TFG in bile duct epithelia with hyperplasia/dysplasia and CCA indicate the significance of TFG in CCA development and progression." (PMID 31754244, 2019). "The TFG-ADGRG7 fusion was identified exclusively in tumour 238 (a preT-immature T-LBL detected in an adult female patient) by the three different detection tools." (PMID 30914738, 2019). "This study reports for the first time, the significance of terminal fucose glycan, TFG, in tumor development and progression of CCA." (PMID 31754244, 2019). "Patients with high TFG expression in tumor tissues exhibited shorter survival than those with low TFG expression." (PMID 31754244, 2019). "In the early stage of infection, through the construction of a suppression subtractive library of transformed cells, the tumor-related gene TFG was screened, and we speculated that TFG was activated in transformed cells." (PMID 36337204, 2022). "Moreover, overexpression of TFG rescued the tumor‐suppressive effect and inhibition of the TGF‐β and AKT/mTOR signaling pathways caused by the down‐regulation of CLTC." (PMID 34185412, 2021). "On a mechanistic level, knockdown of CLTC and TFG could block the activation of ER stress and suppress their pro‐tumor function." (PMID 34185412, 2021). "TFG is also a tumor‐related gene situated on chromosome 3 and is widely expressed in cells." (PMID 34185412, 2021). "Importantly, overexpression of TFG rescued both the tumor‐suppressive effect and inhibition of the TGF‐β and AKT/mTOR pathways caused by CLTC down‐regulation, which indicated that the activity of CLTC was TFG‐dependent." (PMID 34185412, 2021). "In addition, deubiquitinases like USP9X and UBP7 are also highly expressed in both tumor and LN metastatic lesions of the patient with TFG-RET fusion-expressing tumor tissue." (PMID 32345963, 2020). "TFG was implicated in multiple neurodegenerative diseases and oncogenesis 40; thus, SEC23 interaction with TFG could lead to tumor cell growth." (PMID 31595159, 2019).
tumor (continued). "A number of the identified tumour-associated antigens are known to signal via this cascade, HMGN5, TFG, MAEL, SOX15 and Dicckopf-1, the latter of which has been investigated in numerous other biomarker signatures and like TFG interacts via the Wnt co-receptor LRP6." (PMID 34728792, 2022). "Our next step was to investigate whether TFG-RET expression could enable tumor formation in vivo." (PMID 32345963, 2020). "The involvement of TFG and tumor metastasis, however, may depend on tumor origins." (PMID 31754244, 2019). "However, other fusions detected simultaneously in normal and tumour samples (JAK3-INSL3, KANSL1-ARL17A/B and TFG-ADGRG7) could be germ-line fusions genes involved in tumour-maintaining tasks." (PMID 30914738, 2019). "Of note, only two fusions, ZMYM2-FGFR1 (in tumour 408) and TFG-ADGRG7 (in tumour 238), were identified in the same tumour by the three detection methods." (PMID 30914738, 2019). "Subcutaneous injection of Nthy-TFG-RET cells into NOD/SCID mice, after a latency of about 12 weeks, showed tumor formation in mice carrying Nthy-TFG-RET cells, while the control group did not exhibit any tumor growth." (PMID 32345963, 2020). "The stratification did not lead to any significant correlation of TFG expression with clinical features of age, gender, histotype, tumor size, regional lymph node metastasis and staging of the patients." (PMID 31754244, 2019). "Most normal bile duct epithelia (80%) at the adjacent tissues to the tumor had negative signals for TFG, whereas hyperplastic/dysplastic bile ducts (84%) and CCA tissues (66%) had positive TFG signals." (PMID 31754244, 2019). "We chose 4 genes (KIF25, E2F1, DIP2C, TFG) that were present in at least 4 tumor patients, were not present in the healthy population, were detected outside of patients 18, 19, 30, 34, and 38, and have the potential to serve as therapeutic targets or diagnostic and predisposing biomarkers." (PMID 38982214, 2024). "However, the lack of tumor growth in the control group validates the oncogenic potential of TFG-RET." (PMID 32345963, 2020). "Over the latency period, one shall not rule out the possibility that the Nthy-TFG-RET cells might have acquired additional mutations, which ultimately lead to tumor growth." (PMID 32345963, 2020). "However, other fusions detected simultaneously in normal and tumour samples (JAK3-INSL3, KANSL1-ARL17A/B and TFG-ADGRG7) could be germ-line fusions genes involved in cancer predisposition." (PMID 30914738, 2019).
cancer (16 papers, 2014 to 2024). A tumor composed of atypical neoplastic, often pleomorphic cells that invade other tissues. "In three patients, we detected fusions involving a cancer-related gene, such as STK11 and KDM6A, quoted as altered in MPM in the Cosmic database (release v91), or TFG reported in fusions in other cancers." (PMID 34261524, 2021). "Most of the literature surrounding TFG demonstrates an involvement of this protein in cancer, with only two studies suggesting it plays a role in immune regulation." (PMID 24999993, 2014). "One of the key links of TFG to cancer is through fusions of this gene with others." (PMID 38982214, 2024). "The patient’s NGS analyses revealed a TFG::ADGRG7 fusion, which is considered Tier III as clinically insignificant and has been reported in various cancer types as well as in healthy tissue in the literature." (PMID 38866999, 2024). "Notable cases include ETV6-NTRK3, a well-known driver detected in various cancer types including AML, and TFG-ADGRG7, a known event reported in healthy individuals." (PMID 30200994, 2018).
neurodegenerative disease (6 papers, 2017 to 2022). A disorder of the central nervous system characterized by gradual and progressive loss of neural tissue and neurologic function. "Trk-fused gene (TFG) mutations have been identified in patients with several neurodegenerative diseases." (PMID 35121777, 2022). "TFG mutations are related to various other neurodegenerative diseases besides HMSN-P." (PMID 28196470, 2017). "We speculate that mt TFG may possess direct or indirect inhibitory effects on UPS as well as other neurodegenerative diseases." (PMID 28196470, 2017). "Since this is the first study, to our knowledge, using conditional TFG knockout mice, our results not only provide insights into the relationship between TFG and glucose metabolism, but also clues to understanding the pathogenesis of TFG-related neurodegenerative diseases." (PMID 29026155, 2017).
neurological disorders (5 papers, 2020 to 2024). "TFG mutations associated with neurological disorders are classified into two categories based on inheritance patterns: autosomal recessive and autosomal dominant." (PMID 35986567, 2022). "The distinct clinical phenotype in TFG‐related neurological disorders indicate a different pathogenic mechanism for various TFG mutations." (PMID 35986567, 2022). "Thus far, seven neurological disorder‐related mutations in TFG have been identified." (PMID 35986567, 2022).
infection (4 papers, 2021 to 2024). The state of being infected such as from the introduction of a foreign agent such as serum, vaccine, antigenic substance or organism. "In line with this notion, we also observe that HCV promotes TFG translocation to the ERES during infection." (PMID 37338368, 2023). "HeLa cells in which TFG was silenced using four different siRNA exhibited substantially enhanced VSV-GFP infection rates compared to those of cells expressing siNT, as shown in fluorescence microscopy." (PMID 33411856, 2021). "Infection of HeLa cells and primary MRC-5 fibroblasts with SeV led to the TFG-dependent production of detectable amounts of ISG15, ISG54 and ISG56 proteins." (PMID 33411856, 2021).
epithelial neoplasm (1 paper, 2023). A benign or malignant neoplasm that arises from and is composed of epithelial cells. "TFG is a well-known fusion partner in a variety of mesenchymal and epithelial neoplasms of different organs, mostly fused to other receptor tyrosine kinases such as ALK, ROS1, and NTRK." (PMID 36690805, 2023).
TFG also shares sentences with these, for which no sentence is quoted: lung adenocarcinoma (3 papers); anaplastic large cell lymphoma (2); colon cancer (2); peripheral neuropathies (2); spindle cell sarcoma (2); acute leukemia (1); acute myeloid leukemia (1); cervical carcinoma (1); Charcot-Marie-Tooth disease (1); dyslipidemia (1); glioblastoma (1); Impaired glucose tolerance (1); insulin-dependent diabetes mellitus (1); intestinal cancer (1); leukopenia (1); lymph node metastases (1); motor neuron disease (1); multiple myeloma (1); night blindness (1); non-small cell lung carcinoma (1); optic atrophy (1); ovarian carcinoma (1); prostate tumor (1); steatosis (1); stomach cancer (1); thymoma (1); thyroid tumor (1); tongue cancer (1).